RAB3GAP1 (RAB3 GTPase activating protein catalytic subunit 1)
Description:
Catalytic subunit of the Rab3 GTPase-activating (Rab3GAP) complex composed of RAB3GAP1 and RAB3GAP2, which accelerates the otherwise slow GTP hydrolysis catalyzed by Rab proteins. Has GTPase-activating protein (GAP) activity towards various Rab3 subfamily members (RAB3A, RAB3B, RAB3C and RAB3D), RAB5A and RAB43. Additionally, it has guanine nucleotide exchange factor (GEF) activity towards RAB18, promoting GDP release from RAB18 and the conversion of inactive RAB18-GDP to the active form RAB18-GTP. Recruits and stabilizes RAB18 at the cis-Golgi membrane in fibroblasts where RAB18 is most likely activated. Also involved in RAB18 recruitment at the endoplasmic reticulum (ER) membrane where it maintains proper ER structure. Required for normal eye and brain development. May participate in neurodevelopmental processes such as cell proliferation, migration and differentiation before synapse formation, and is involved in regulating non-synaptic vesicular release of neurotransmitters.
Synonyms: KIAA0066; RAB3GAP; RAB3GAP130; WARBM1; MARTS2; P130
Tractability: PROTAC: ubiquitination databases record sites on it; its protein half-life has been measured.
Gene: Protein-coding gene on chromosome 2 (135,052,283 to 135,176,667, forward strand). Ensembl gene ENSG00000115839.
Subcellular location: Cytoplasm; Endoplasmic reticulum; Golgi apparatus, cis-Golgi network
Subcellular location (Human Protein Atlas): Nucleoplasm; Cytosol
Pathways (Reactome):
Vesicle-mediated transport: COPI-independent Golgi-to-ER retrograde traffic; RAB GEFs exchange GTP for GDP on RABs
Gene Ontology:
Molecular function: GTPase activator activity; guanyl-nucleotide exchange factor activity; protein binding; small GTPase binding
Biological process: brain development; camera-type eye development; establishment of protein localization to endoplasmic reticulum membrane; face morphogenesis; hypothalamus development; lipid droplet organization; positive regulation of autophagosome assembly; positive regulation of endoplasmic reticulum tubular network organization; positive regulation of protein lipidation; excitatory postsynaptic potential; positive regulation of glutamate neurotransmitter secretion in response to membrane depolarization; Rab protein signal transduction; regulation of calcium ion-dependent exocytosis of neurotransmitter; regulation of short-term neuronal synaptic plasticity
Cellular component: cis-Golgi network; cytoplasm; endoplasmic reticulum; endoplasmic reticulum tubular network; extracellular exosome; Golgi apparatus; GTPase complex; lipid droplet; protein-containing complex; cytosol; endoplasmic reticulum membrane; postsynapse
Genetic constraint (gnomAD): Loss-of-function variants: 78 observed, 118 expected, observed/expected ratio (o/e) 0.66, 90% interval 0.55 to 0.8. The upper end of that interval is the gene's LOEUF score, 0.8, which puts it in group 3 of 6, group 1 being the genes least tolerant of losing a copy. Missense variants: 935 observed, 1,122.1 expected, observed/expected ratio (o/e) 0.83, 90% interval 0.79 to 0.88. Synonymous variants: 335 observed, 390.4 expected, observed/expected ratio (o/e) 0.86, 90% interval 0.78 to 0.94.
Gene-disease validity (ClinGen):
ClinGen rates the evidence that RAB3GAP1 causes each of these diseases.
Warburg micro syndrome (autosomal recessive): Definitive.
Homologues: Orthologues: chimpanzee RAB3GAP1 (99% identical), macaque RAB3GAP1 (99% identical), rabbit RAB3GAP1 (96% identical), guinea pig RAB3GAP1 (95% identical), dog RAB3GAP1 (94% identical), mouse Rab3gap1 (93% identical), rat Rab3gap1 (93% identical), tropical clawed frog rab3gap1 (79% identical), pig RAB3GAP1 (72% identical), zebrafish rab3gap1 (70% identical), Drosophila melanogaster Rab3GAP1 (30% identical), Caenorhabditis elegans rbg-1 (23% identical).
Diseases named in the same sentence as RAB3GAP1 in open-access papers:
RAB3GAP1 is named in the same sentence as 41 diseases in open-access papers, as found by Europe PMC text mining. Sharing a sentence is not in itself a finding about the gene and the disease. The quoted sentences say what the papers report.
Warburg micro syndrome (15 papers, 2013 to 2026). Micro syndrome is an autosomal recessive disorder caracterised by ocular and neurodevelopmental defects and by microgenitalia. "A 4‐year‐old male patient diagnosed with Warburg Micro Syndrome based on a homozygous c.2709 + 1G>T pathogenic splice site variant in the RAB3GAP1 gene." (PMID 41466769, 2026). "Warburg Micro Syndrome (WARBM, ORPHA: 2510), also known as Micro Syndrome, is a RD caused by mutations in RAB3GAP1 and TBC1D20 genes." (PMID 37160609, 2023). "We extended our sterol profiling with additional experiments using RAB3GAP1-deficient primary fibroblasts from an individual with Micro syndrome together with control cells derived from a parent." (PMID 37774976, 2023). "We describe a novel homozygous splice site mutation in RAB3GAP1 associated with Warburg Micro syndrome in a Chinese patient." (PMID 33466118, 2021). "The patient was diagnosed with Warburg Micro syndrome based on clinical manifestations, additional medical examinations, and the novel homozygous c.75–2A>C mutation in RAB3GAP1." (PMID 33466118, 2021). "This case report describes a novel mutation in the RAB3GAP1 gene associated with Warburg Micro syndrome." (PMID 33466118, 2021). "The patient was diagnosed with Warburg Micro syndrome based on clinical manifestations, as well as a novel homozygous mutation in RAB3GAP1: c.75–2A>C." (PMID 33466118, 2021). "In this paper, we present the first Iranian patients with pathogenic variants in RAB3GAP1 causing Warburg micro syndrome." (PMID 34702808, 2021). "Mutations in RAB3GAP1 are associated with Warburg micro syndrome, a rare autosomal recessive syndrome characterized by microcephaly, severe mental retardation and cataracts." (PMID 23593153, 2013). "Mutations in RAB18, RAB3GAP1, RAB3GAP2, and TBC1D20 have caused Warburg micro syndrome, a rare autosomal recessive multisystem disorder, suggesting that RAB3GAP1, RAB3GAP2, and TBC1D20 might play roles in PRRSV-2 replication." (PMID 38607975, 2024). "The c.75–2A>C mutation in RAB3GAP1 expands the spectrum of known mutations in this gene, and it may be associated with Warburg Micro syndrome." (PMID 33466118, 2021). "In two patients with clinically recognizable syndromes (i.e. Warburg Micro syndrome and Aicardi-Goutières syndrome), mutations in RAB3GAP1 (patient 1) and RNASEH2B (patient 26) related to these conditions were identified during their diagnostic work-up as well as by whole-exome sequencing." (PMID 26846091, 2016). "Biallelic loss-of-function variants in RAB18, RAB3GAP1, RAB3GAP2, or TBC1D20 cause the autosomal recessive condition Warburg Micro syndrome (Mendelian Inheritance in Man IDs: 600118, 614222, 614225, 615663, and 212720)." (PMID 37774976, 2023). "RAB18, RAB3GAP1, RAB3GAP2 and TBC1D20 are each mutated in Warburg Micro syndrome, a rare autosomal recessive multisystem disorder." (PMID 26063829, 2015). "Here we report a Chinese patient with Warburg Micro syndrome associated with an RAB3GAP1 mutation never described before." (PMID 33466118, 2021). "Loss-of-function mutations in Rab3GAP1 and Rab3GAP2 produce clinically almost indistinguishable conditions, Warburg Micro syndrome and Martsolf syndrome, characterized by brain, eye, and endocrine abnormalities." (PMID 25710274, 2015). "The second case (P2) had a suspected diagnosis of Warburg Micro syndrome (OMIM #600118) and a 4 bp deletion affecting the splice junction site of RAB3GAP1 exon 21 was previously detected by Sanger sequencing (NM_012233.3:c.2387_2390del)." (PMID 37558402, 2023). "RAB3GAP1 and RAB3GAP2 were characterized as forming a complex with GAP activity towards Rab3 isoforms before their involvement in Micro syndrome, or that of RAB18, was known." (PMID 26063829, 2015).
Martsolf syndrome (7 papers, 2014 to 2022). "To date, only three pathogenic variants related to Martsolf syndrome were detected in RAB3GAP1." (PMID 36553631, 2022). "Furthermore, in the tunicates Ciona robusta and Phallusia mammillata, Rimbp forms a triplet with Rab3Gap1, which in vertebrates is implicated in Warburg and Martsolf syndromes and, like Rimbp proteins, is an effector of Rab3 proteins, and Chmp2." (PMID 32867148, 2020). "44% of Martsolf syndrome cases have mutations in RAB3GAP1 or RAB3GAP2, which perturb but do not completely abolish the expression or function of the encoded protein." (PMID 30856165, 2019).
microcephaly (6 papers, 2012 to 2024). A congenital or acquired developmental disorder in which the circumference of the head is smaller than normal for the person's age and sex. "RAB3GAP1 is strongly associated with microcephaly, consistent with aberrations in FA trafficking to the brain, the organ most associated with structural use of FAs, and a function likely to be affected by altered discrimination of FAs by chain length." (PMID 29652918, 2018). "Rab3Gap1 mutations cause Warberg microsyndrome, a disease characterised by microcephaly, microphthalmia, microcornia, cataracts, optic atrophy, cortical dysplasia, mental retardation, spastic diplegia, and hypogonadism." (PMID 23685254, 2013). "Mutations in RAB3GAP1 and RAB3GAP2 cause the autosomal recessive Warburg Micro and Martsolf syndromes, which involve congenital cataracts, microphthalmia, postnatal microcephaly and developmental delay." (PMID 22870394, 2012).
microphthalmia (5 papers, 2012 to 2024). Congenital or developmental anomaly in which the eyeballs are abnormally small. "Among other characteristics, individuals homozygous for RAB3GAP1 present failure to thrive, intellectual disability, corpus callosum hypoplasia, diffuse cortical or subcortical atrophy, congenital cataracts, microcornea and microphthalmia." (PMID 37160609, 2023). "The RAB3GAP1 SINE insertion described in Alaskan Huskies with a Warburg-like syndrome, which includes microphthalmia results in part of the affected exon being spliced out as an intron, but this is not the case of our insertion." (PMID 38682429, 2024).
keratoconus (3 papers, 2014 to 2018). A degenerative, structural disorder of the eye, characterized by a cone-shaped protrusion of the cornea. "In another GWAS, Li and colleagues identified a SNP (rs4954218) located near RAB3GAP1 (OMIM 602536) as a potential susceptibility locus for keratoconus in Caucasian cohorts from USA." (PMID 25254113, 2014). "Similarly, other candidate genes identified by GWAS including HGF, RAB3GAP1, LOX, MPDZ, NFIB, BANP, and ZNF469 may be important risk factors for keratoconus and require replication studies in other populations." (PMID 25254113, 2014).
colorectal cancer (2 papers, 2020 to 2021). A primary or metastatic malignant neoplasm that affects the colon or rectum. "Our study demonstrated that the phosphorylation status of hnRNP A0 was augmented in colorectal cancer tissues compared with normal tissues, and this enhanced cancer progression by binding to and stabilizing RAB3GAP1 mRNA in colorectal cancer cells." (PMID 34830186, 2021). "The knockdown of hnRNP A0 induced apoptosis in colorectal cancer cells (except in non-cancer epithelial cells) because of minimal binding between hnRNP A0 and RAB3GAP1 mRNA in non-cancerous epithelial cells." (PMID 34830186, 2021).
polyneuropathy (2 papers, 2015 to 2023). A disease or disorder affecting more than one nerve. "In Black Russian Terriers with polyneuropathy with ocular abnormalities and neuronal vacuolation, a single nucleotide deletion (c.743delC) within the RAB3GAP1 gene was pinpointed as the causal variant." (PMID 38003185, 2023).
schizophrenia (2 papers, 2019 to 2022). A major psychotic disorder characterized by abnormalities in the perception or expression of reality. "In our study, we detected by LC-MS/MS that these proteins, specifically BDNF, GMF-β, and the 115-kDa isoform of RAB3GAP1, are downregulated in schizophrenia, with significantly reduced levels being detected in the plasma of schizophrenic patients." (PMID 31849731, 2019). "In conclusion, GMF-β, BDNF, and 115-kDa isoform of RAB3GAP1 showed significantly reduced levels in plasma of patients with schizophrenia, thus making them potential biomarkers in schizophrenia." (PMID 31849731, 2019). "Of the total of 34 proteins screened, 5 proteins associated with psychoneuroimmune pathways in schizophrenia were analyzed, which could be potential new analytes: drebrin, GMF-β, BDNF, RAB3GAP1, and attractin." (PMID 31849731, 2019). "In conclusion, there is a great potential for BDNF, GMF-β, and the 115-kDa isoform of RAB3GAP1 proteins to act as possible biomarkers of schizophrenia, and they may even differentiate early stages (e.g. BDNF) from later stages (e.g. GMF-β) of the disease." (PMID 31849731, 2019).
Alzheimer disease (1 paper, 2024). A progressive, neurodegenerative disease characterized by loss of function and death of nerve cells in several areas of the brain leading to loss of cognitive function such as memory and language. "Several variants mapped to PVRL2, TOMM40, LCMT1, and RAB3GAP1 genes previously associated with Alzheimer disease." (PMID 38291454, 2024).
glaucoma (1 paper, 2017). Increased pressure in the eyeball due to obstruction of the outflow of aqueous humor. "We found that FOXC1 knockdown, through regulation of RAB3GAP1, RAB3GAP2 and SNAP25, leads to decrease in both intracellular and extracellular levels of MYOC, tying these genes into a common pathway of glaucoma pathogenesis." (PMID 28575017, 2017).
cancer (3 papers, 2019 to 2021). A tumor composed of atypical neoplastic, often pleomorphic cells that invade other tissues. "The present study showed that the cancer-specific phosphorylation of heterogeneous ribonucleoprotein (hnRNP) A0 maintains tumor mitotic events through the RAB3GAP1-mediated stabilization of ZWINT1." (PMID 32303675, 2020). "Notably, hnRNP A0 was essential for the alignment of chromosomes at the equatorial plane during cell division through the inhibition of the proteasomal degradation of ZWINT1, which is regulated by RAB3GAP1 in cancer cells." (PMID 32303675, 2020). "In conclusion, we showed that phosphorylated hnRNP A0, which is highly expressed in cancer cells, was essential for the accurate alignment of chromosomes at the equatorial plane during cell division in cancer cells, which was mediated by the stabilization of RAB3GAP1 mRNAs." (PMID 32303675, 2020). "On the other hand, RAB3GAP1 also plays an important role in the autophagic pathway that results in the intercellular accumulation of proteins, whose dysregulation is related with several conditions such as cancer and cardiovascular or neurodegenerative diseases." (PMID 31849731, 2019). "Collectively, hnRNP A0-stabilized RAB3GAP1 inhibits the Rab3-induced degradation of ZWINT1, which is essential for the regulation of the alignment of the chromosomes at the equatorial plane during metaphase in cancer cells, thereby maintaining excessive cell division." (PMID 32303675, 2020).
tumor (1 paper, 2020). "The tumor progression was reduced in hnRNP A0-knockdown or RAB3GAP1-knockdown cells in in vivo carcinogenesis and xenograft model mice." (PMID 32303675, 2020).
RAB3GAP1 also shares sentences with these, for which no sentence is quoted: cataract (3 papers); congenital cataracts (3); Warburg micro syndrome 1 (3); developmental delay (2); Microcornea (2); Aicardi-Goutières syndrome (1); Atrophy (1); breast carcinoma (1); cardiac failure (1); Charcot-Marie-Tooth disease type 2B (1); cortical dysplasia (1); demyelinating peripheral neuropathy (1); dilated cardiomyopathy (1); endometriosis (1); Failure to thrive (1); hypogonadism (1); hypogonadotropic hypogonadism (1); infection (1); Intellectual disability (1); Leber congenital amaurosis (1); melanoma (1); neurodegenerative disease (1); neurological disorders (1); optic atrophy (1); Osteopenia (1); thoracic aortic aneurysm (1); Type 1 diabetes (1); Vici syndrome (1); Warburg syndrome (1).